USP32 (ubiquitin specific peptidase 32)
Diseases named in the same sentence as USP32 in open-access papers (continued):
Sharing a sentence is not in itself a finding about the gene and the disease.
colon cancer (1 paper, 2026). "To illustrate the mechanism of USP32-mediated stabilization of PD-L1 in colon cancer progression, we sought to investigate the physical association between USP32 and PD-L1 proteins." (PMID 41356798, 2026). "We identified USP32 as a uniquely expressed gene that is correlated with PD-L1 expression in immune cell types of human colon cancer tissues, in contrast to human liver cancer tissues." (PMID 41356798, 2026). "Particularly showing positive correlation between USP32 and PD-L1 in colon cancer cell lines with a r value of 0.7317." (PMID 41356798, 2026). "Like PD-L1, USP32 is more highly expressed in colon cancer than control group, particularly elevated expression was observed in specific cell types including T-cells, macrophages, classical monocytes, mesothelial, and endothelial cells." (PMID 41356798, 2026). "We analyzed the correlation between the expression of USP32 and PD-L1 in colon cancer compared to the control group." (PMID 41356798, 2026). "Interestingly, USP32 and USP12 have been repeatedly found at elevated levels in T-cells, macrophages, and classical monocytes associated with colon cancer compared with levels in the control group." (PMID 41356798, 2026). "Because scRNA-seq analysis revealed that USP32 expression was elevated in colon cancer, we hypothesized that knockout of the USP32 gene could impede cell proliferation and colon cancer growth in vitro." (PMID 41356798, 2026). "Moreover, Kaplan-Meier analysis of TCGA survival data indicated that elevated expression of USP32 and PD-L1 correlates with worse survival in colon cancer patients, indicating that high USP32 expression may be associated with an adverse prognosis in colon cancers." (PMID 41356798, 2026). "USP32, USP1, USP37, USP12, and USP6 are elevated in macrophages, while USP32, USP9X, USP46, USP12, USP36, and USP24 are upregulated in classical monocytes of colon cancer relative to the control group." (PMID 41356798, 2026). "Our in-depth scRNA-seq analysis revealed a significant correlation between the expression of PD-L1 and ubiquitin-specific protease 32 (USP32) within the immune cell types from human and mouse colon tumor tissues." (PMID 41356798, 2026).
endometrial cancer (1 paper, 2022). Primary or metastatic malignant neoplasm involving the endometrium (mucous membrane that lines the endometrial cavity). "The three LoF-intolerant genes (AKAP11, GRID1, and USP32) are all mutated in 5–8% of all Endometrial cancers in TCGA36." (PMID 35906355, 2022).
gastrointestinal stromal tumor (1 paper, 2023). "Recent research has revealed that the USP32-Rab35 axis is crucial for controlling treatment resistance in gastrointestinal stromal tumors." (PMID 37679322, 2023). "USP32 promotes the exocrine secretion of imatinib-resistant gastrointestinal stromal tumors by decreasing the Lys48 (K48) ubiquitination of Rab35, protecting it from proteasome destruction." (PMID 37679322, 2023). "Their research suggests that individuals with gastrointestinal stromal tumors resistant to imatinib may benefit from focusing on the USP32-Rab35 axis as a potential therapeutic target." (PMID 37679322, 2023). "In gastrointestinal stromal tumors that are imatinib-resistant, ETV1 increases the expression of USP32." (PMID 37679322, 2023).
lentivirus infection (1 paper, 2025). Virus diseases caused by the Lentivirus genus. "To validate whether LBT induces ferroptosis by targeting USP32, we established the stable overexpression of USP32 in H520 and H1703 cells using lentivirus infection." (PMID 40136417, 2025).
leukemia (1 paper, 2022). A malignant (clonal) hematologic disorder, involving hematopoietic stem cells and characterized by the presence of primitive or atypical myeloid or lymphoid cells in the bone marrow and the blood. "Additionally, USP32 mutations have been found in human leukemia cells, which frequently carry recurrent cohesin deficits, including mutations in SMC131 and RAD2132." (PMID 35906355, 2022).
lung carcinoma (1 paper, 2021). "However, SLC35F2 was highly upregulated in colon and lung cancer tissues and relative low levels of USP32 were observed in the respective tissues." (PMID 34815782, 2021). "The expression patterns of USP32 and SLC35F2 in human breast (n = 21), colon (n = 32), and lung cancers (n = 32) obtained from ISU Abxis tissue microarray were subjected to immunohistochemistry staining." (PMID 34815782, 2021).
metastatic tumors (1 paper, 2016). "Metabolic advantage is a feature of metastatic tumors and might be mediated by overexpression of VLDLR, USP32, and PITPINC1." (PMID 27136531, 2016).
pulmonary hypertension (1 paper, 2025). Increased pressure within the pulmonary circulation due to lung or heart disorder. "ROC analysis validated their diagnostic effectiveness, with USP32 and ZNF655 exhibiting ROC values above 0.75 in both the experimental and validation datasets, underscoring their significance in pulmonary hypertension diagnosis." (PMID 40924716, 2025). "This approach yielded complex networks, illustrating the intricate regulatory relationships involving USP32 and ZNF655 within pulmonary hypertension pathology." (PMID 40924716, 2025).
testicular germ cell tumor (1 paper, 2022). A germ cell tumor arising from the testis. "The result showed that all the rest four USPs were aberrantly expressed in several other tumors with USP32 lower expression in testicular germ cell tumors and USP33 higher expression in thymoma." (PMID 36582601, 2022).
uremia (1 paper, 2013). A clinical syndrome associated with the retention of renal waste products or uremic toxins in the blood. "However, probe sets of the protein-degradation machinery, e.g. UBE2E1, USP32, UBE2Q2, and UBR3 were inhibited in uremia, indicating that evaluation of the ubiquitin-proteosome machinery requires more detailed investigation." (PMID 23809614, 2013).
cancer (17 papers, 2019 to 2026). A tumor composed of atypical neoplastic, often pleomorphic cells that invade other tissues. "Among the largest families of DUBs, the ubiquitin-specific peptidase (USP) family, USP32 has been implicated in the progression of various diseases, including cancer, neurodegenerative disorders, regulation of the endosomal transport and autophagy." (PMID 41184228, 2025). "According to several studies, high levels of USP32 expression are associated with poor prognosis in various malignant tumors." (PMID 37679322, 2023). "USP32 is associated with pathways related to cell behaviors and cancer signaling, and its expression is significantly correlated with the infiltration of immune cells in the TME." (PMID 37957631, 2023). "Recently, a number of studies have implicated USP32 in the pathogenesis of various cancers, as well as Parkinson’s disease." (PMID 30926795, 2019). "However, among these cancer types, we noticed that high USP32 expression was significantly associated with several poorer prognostic indicators (OS, PFI and DFI) only in HCC." (PMID 37957631, 2023). "Additionally, we examined TCGA data sets to find USP32 expression in human cancer tissues that were linked with nearby normal tissues." (PMID 37679322, 2023). "Since the PI3K/AKT/mTOR axis is the fundamental for the regulation of cell proliferation and linked to multidrug resistance in cancer 33,34, we next investigated whether loss-of-USP32 can modulate this pathway." (PMID 34815782, 2021). "For this reason, USP32 has been associated with growth rate of cancer cells." (PMID 32296077, 2020). "The correlation between USP32 and PD-L1 expression across wide panel of cancer cells using the CCLE database showed that the high score for USP32 mRNA level was proportional to the PD-L1 mRNA level with r value 0.8639." (PMID 41356798, 2026). "Analysis of the TCGA database has yielded the expression patterns of USP32 in various malignant tumors." (PMID 40607251, 2025). "Mechanistically, the abnormal activation of USP32 contributes to cancer cell proliferation, invasion and drug resistance via regulating the expression of downstream factors such as SMAD, SHMT2, SLC35F2 and FDFT1." (PMID 40122703, 2025). "In recent years, the USP32 gene, which maps to 17q23, has been found to be overexpressed in several kinds of cancers such as breast cancer, epithelial ovarian cancer, small cell lung cancer, glioblastoma, gastric cancer and liver cancer." (PMID 40122703, 2025). "Accumulating evidence has demonstrated that USP32 is overexpressed in various tumors and is significantly involved in tumor development, cancer-related signaling, and protein stability." (PMID 40136417, 2025). "Aberrant expression of USP32 triggers certain diseases such as Parkinson’s, Fragile X Syndrome, Chronic Kidney Disease and Cancer." (PMID 39030175, 2024). "Recent research has demonstrated the high expression of USP32 in a range of cancers and its role in the initiation and progression of cancer." (PMID 39030175, 2024). "The increased expression of USP32 in different cancers is a necessary condition for cell proliferation and tumorigenesis." (PMID 37679322, 2023). "In order to fully understand the mechanism of action of USP32 in different malignant tumors, researchers need to learn USP32 and its regulation of downstream targets." (PMID 37679322, 2023). "In recent years, the importance of USP32 continues to be revealed, especially in cancer, where USP32 is often disordered." (PMID 37679322, 2023). "Cancer cell proliferation and migration can be stopped in vitro by inhibiting USP32, and tumor growth can be stopped in vivo by down-regulating the USP32 gene." (PMID 37679322, 2023). "In subsequent studies, several studies supported that USP32 functions as a universal oncogene in cancer." (PMID 37957631, 2023). "As a member of the USPs family, USP32 controls DNA damage repair, cell cycle, cancer-related signaling, and protein stability." (PMID 37679322, 2023).
cancer (continued). "We investigated the expression of USP32 in various malignant tumors by using the TCGA database and assessed the expression of USP32 in 33 tumor tissues and paraneoplastic tissues." (PMID 37679322, 2023). "In their research, they discovered that USP32 can speed up the transition of the cell cycle from the G0 phase to the G1 phase, start DNA replication, and so enhance the growth of cancer cells." (PMID 37679322, 2023). "According to TCGA-LIHC, GSE36376, GSE102079, GSE164760, GSE14426 and GSE14520 datasets, the mRNA expression of USP32 was markedly higher in HCC samples than in non-cancer tissues (p-value < 0.0001)." (PMID 37957631, 2023). "Through a series of preliminary pan-cancer analyses, we discovered that USP32 is significantly overexpressed in several cancer types such as BC, cholangiocarcinoma, esophageal carcinoma, head and neck squamous cell carcinoma, HCC and GC." (PMID 37957631, 2023). "YM155-resistant cancer cells in particular exhibited elevated expression of USP32 and low expression of SLC35F2." (PMID 34815782, 2021). "In contrast, low USP32-expressing cancer cells such as PC3, SW480 and HCT116 was associated with relatively high SLC35F2 expression (lanes 1, 2 and 5), suggesting that the USP32 is negatively correlated with SLC35F2 protein in several human cancer cell lines." (PMID 34815782, 2021). "Our approach to inhibiting USP32 to increase chemotherapeutic efficacy can be expanded to YM155-based cancer treatment in cells resistant to YM155 because of low SLC35F2." (PMID 34815782, 2021). "In conclusion, our findings provide a new insight into the expression and function of USP32 in cancer." (PMID 32226309, 2020). "In addition, IHC staining shows that USP32 protein expression is relatively higher in cancer tissues compared with non‐cancer samples." (PMID 40122703, 2025). "Ubiquitin‐specific protease 32 (USP32) plays a key role in cancer progression." (PMID 40122703, 2025). "The expression of USP32 was higher in cancer tissues compared to normal tissues adjacent to cancer." (PMID 39030175, 2024). "The expression of USP32 is often out of balance, especially in cancer." (PMID 37679322, 2023). "Therefore, a possible target for cancer therapy is USP32, which has been shown an important role in many malignant tumors and chemotherapy resistance." (PMID 37679322, 2023). "The therapeutic importance of USP32 in cancer treatment remains to be further proven." (PMID 37679322, 2023). "Ubiquitin-specific protease 32 (USP32) is a highly conserved gene that promotes cancer progression." (PMID 37957631, 2023). "Similar to the result of previous study, USP32 may also participate in the process of choline metabolism of cancer." (PMID 36582601, 2022). "The results imply that USP32 inhibition in cancer cells resistant to YM155 due to reduced SLC35F2 expression may be an effective YM155-based cancer treatment." (PMID 34815782, 2021). "However, several studies have reported that overexpression of USP32 promotes tumorigenesis and drug resistance in different cancer types 38,39." (PMID 34815782, 2021). "Furthermore, our study provides evidence that USP32-targeted therapies may serve as efficient approaches for treating ferroptosis-driven cancers." (PMID 40136417, 2025). "Ubiquitin-specific protease 32 (USP32), a deubiquitylating enzyme that controls the ubiquitin process, is overexpressed in multiple cancers and serves as a promising therapeutic target for cancer therapy." (PMID 40136417, 2025). "However, the influence of USP32 on ferroptosis in cancer cells remains unclear." (PMID 40136417, 2025). "A series of in vitro and in vivo experiments were conducted to reveal the relationship between USP32 and SLC35F2 on YM155-mediated DNA damage in cancer cells." (PMID 34815782, 2021). "The expression of USP32 and SLC35F2 was negatively correlated across a panel of tested cancer cell lines." (PMID 34815782, 2021).
cancer (continued). "We determined that USP32, a membrane protein, can confer resistance to cellular uptake of YM155 by destabilizing endogenous expression of SLC35F2 in cancer cells." (PMID 34815782, 2021). "Although the multiple functions of USP32 in cancer have been widely reported, no studies have investigated the expression and potential role of USP32 in CRC." (PMID 40122703, 2025). "Although the roles of USP32 in cancer are widely reported, there are no studies that have focused on the role of USP32 in CRC." (PMID 40122703, 2025). "In 2021, USP32 was found to be overexpressed in epithelial ovarian cancer (EOC), particularly in metastatic peritoneal tumors, and it positively regulates the proliferation and epithelial-mesenchymal transition (EMT) capabilities of cancer cells." (PMID 37957631, 2023). "Given that USP32 is overexpressed in cancer cells, we speculated that the efficacy of YM155 uptake could be predicted by USP32 expression." (PMID 34815782, 2021). "This led us to hypothesize that the high USP32 expression and corresponding low SLC35F2 expression makes cancer cells resistant to YM155 and vice versa in case of sensitive cells." (PMID 34815782, 2021). "Here, CRISPR-based dual-screening strategies (cell viability and protein stabilization) successfully identified USP32 as a novel and bona fide candidate that governs resistance for YM155 uptake by destabilizing SLC35F2 protein levels in a wide range of cancer cells." (PMID 34815782, 2021). "The high score for USP32 mRNA level in any given cancer cell line was inversely proportional to the SLC35F2 mRNA, which suggests a significant negative correlation between USP32 and SLC35F2 with a r value of -0.1789." (PMID 34815782, 2021). "To corroborate the negative correlation between USP32 and SLC35F2, we estimated the expression of these two proteins in several cancers." (PMID 34815782, 2021).
tumor (13 papers, 2007 to 2026). "In contrast, USP32-KO reconstitution with either USP32 or PD-L1 was associated with an increase in tumor volume and weight." (PMID 41356798, 2026). "Notably, we also investigated the association between USP32 and the tumor microenvironment (TME) of HCC." (PMID 37957631, 2023). "The mice xenograft tumor tissues exhibited low expression of PD-L1 in USP32-KO group, while reconstitution with either USP32 or PD-L1 restored PD-L1 expression." (PMID 41356798, 2026). "In our study, we explored the expression and clinical significance of USP32 in CRC as well as its relationship with the tumour microenvironment (TME)." (PMID 40122703, 2025). "USP32 participates in tumor growth and resistance to therapy via the deubiquitination modification of tagged substrates, such as Rap1b and SLC35F2, suggesting that USP32 is a potential therapeutic target." (PMID 40136417, 2025). "USP32 is expressed not only in tumour cells but also in B cells, mast cells, myeloid cells, plasma cells, stromal cells and TNKILC cells." (PMID 40122703, 2025). "The results of in vivo studies showed that USP32 overexpression significantly promoted CT26 tumour progression." (PMID 40122703, 2025). "We discovered that USP32 expression levels significantly regulate the proliferation and migration of NSCLC tumor cells, which led us to believe that USP32 was an oncogene in NSCLC." (PMID 39030175, 2024). "In this review, we focus on the multiple mechanisms of USP32 in various tumor types and show that USP32 controls the stability of many distinct proteins." (PMID 37679322, 2023). "Tumor weight derived from the USP32-downregulation group was significantly lower than those derived from control group, verifying the oncogenic role of USP32 in the growth of HCC tumors." (PMID 37957631, 2023). "We know that USP32 is widely expressed in mammals and is involved in tumor activity, fragile X syndrome and chronic nephropathy." (PMID 37679322, 2023). "In the investigation of drug resistance in tumor cells, USP32, a membrane protein, can result in resistance to the anticancer medication YM155 by interfering with the steady expression of SLC35F2." (PMID 37679322, 2023). "In the current study, we discovered that USP32 is also overexpressed and promotes tumor progression in HCC." (PMID 37957631, 2023). "In 2020, our laboratory first reported that USP32 plays an oncogenic role in gastric carcinoma (GC) through promoting tumor growth, metastasis, and cisplatin resistance." (PMID 37957631, 2023). "In GISTs, USP32 protects Ras-related protein Rab-35 (Rab35) from proteasomal degradation, leading to tumor resistance to Imatinib, a tyrosine kinase inhibitor that is wildly used to combat GISTs." (PMID 37957631, 2023). "Elevated USP32 expression was significantly related to the clinical stage (P < 0.0001), tumor histological grade (P < 0.01), T classification (P < 0.0001), N classification (P < 0.001), and M classification (P < 0.01)." (PMID 37957631, 2023). "Tumor xenograft experiments in nude mice were also performed to validate the role of USP32 in GBM development." (PMID 35440702, 2022). "In the present study, we found that the USP32 expression in PDAC tissues was significantly higher than that in normal pancreatic tissues and also significantly associated with tumor grade, tumor stage, and immune infiltration." (PMID 36582601, 2022). "The ablation of the USP32 gene led to a reduction in tumor development in a mouse xenograft study, suggesting that inhibition of USP32, which subsequently reduces PD-L1 protein levels, might be a viable therapeutic strategy for the treatment of CRC." (PMID 41356798, 2026). "The tumor volume and weight was reduced in the mice injected with USP32-KO." (PMID 41356798, 2026). "In addition, high USP32 expression plays a crucial role in tumor growth, metastasis, immune infiltrates, and chemoresistance via the deubiquitination of various substrate proteins, such as Smad2, SHMT2, FDFT1, Rab7, SLC35F2, and BAG3." (PMID 40136417, 2025).